RN7SL460P (RNA, 7SL, cytoplasmic 460, pseudogene)
Gene: Miscellaneous RNA gene on chromosome X (77,885,377 to 77,885,634, forward strand). Ensembl gene ENSG00000263410.
Homologues: Orthologues: chimpanzee Metazoa_SRP (99% identical), macaque Metazoa_SRP (49% identical). Paralogues in human: RN7SL774P (83% identical), RN7SL96P (82% identical), Metazoa_SRP (82% identical), RN7SL835P (81% identical), RN7SL134P (81% identical), RN7SL784P (81% identical), Metazoa_SRP (81% identical), RN7SL470P (81% identical), RN7SL474P (81% identical), RN7SL190P (80% identical), RN7SL819P (80% identical), Metazoa_SRP (80% identical), and 706 more.